CUL4A (cullin 4A)
Diseases named in the same sentence as CUL4A in open-access papers (continued):
Sharing a sentence is not in itself a finding about the gene and the disease.
lung carcinoma (continued). "Knockdown of the Cul4A expression by shRNA in lung cancer cells resulted in decreased cellular proliferation and growth in lung cancer cells." (PMID 26969027, 2016). "Although our findings are similar to a previous study 10, which emphasized on the overexpression of Cul4A with enhanced growth of lung cancer cells and increased sensitivity to erlotinib, which is a target therapy drug for lung cancer." (PMID 26969027, 2016). "Overexpression of Cul4A in lung cancer cells were performed in retroviral transfection of Myc‐tagged Cul4A in H460, H157 and H322 lung cancer cells using pBABE‐puro vector." (PMID 26969027, 2016). "Previous studies have shown that Cul4A is amplified in malignant pleural mesothelioma 8, breast 9, lung cancer 10 and liver cancers." (PMID 26969027, 2016). "Increased chemosensitivity to cisplatin was also observed in Cul4A knockdown H157, H322 and H460 lung cancer cells." (PMID 26969027, 2016). "As a result, we also evaluated changes of cell cycle after Cul4A knockdown in lung cancer cells and G0/G1 cell cycle arrest was also observed in the lung cancer cells studied." (PMID 26969027, 2016). "Increased sensitivity to gemcitabine, a chemotherapy drug, was also noted in those Cul4A knockdown lung cancer cells." (PMID 26969027, 2016). "Significantly decreased tumour growth after Cul4A knockdown was observed in both H460 and H157 lung cancer cells." (PMID 26969027, 2016). "Cul4A knockdown was performed by retrovirus‐transfected shRNA in H157, H322 and H460 lung cancer cells." (PMID 26969027, 2016). "Because knockdown of Cul4A increased chemosensitivity to gemcitabine in H460 and H157 lung cancer cell lines, we studied the effects of Cul4A knockdown on chemosensitivity to gemcitabine in H460 and H157 xenograft models." (PMID 26969027, 2016). "With the purpose to observe the growth of lung tumours after Cul4A knockdown, lung cancer xenograft models using H157 and H460 stable lung cancer cells were established." (PMID 26969027, 2016). "Decreased expression (50–70%) of Cul4A after shRNA knockdown was noted in the lung cancer cells studied." (PMID 26969027, 2016). "We further studied chemosensitivity to gemcitabine after Cul4A overexpression in H460 and H157 lung cancer cells and observed that significantly increased IC50 was observed in these two cell lines compared to empty virus transfected controls." (PMID 26969027, 2016). "In our work, we emphasized the effects of Cul4A knockdown on lung cancer growth and increased chemosensitivity to gemcitabine, cisplatin and pemetrexed, which are a commonly used chemotherapy drugs, in lung cancer in vitro and in vivo." (PMID 26969027, 2016). "In this study, the role of Cul4A in the growth and chemosensitivity in lung cancer cells were studied." (PMID 26969027, 2016). "With the purpose to evaluate the association of Cul4A and drug sensitivity to chemotherapy drugs in lung cancer cells, we treated Cul4A shRNA transfected stable H157, H322 and H460 lung cancer cells with gemcitabine, which is a chemotherapy agent." (PMID 26969027, 2016). "Through in vitro and in vivo studies, we observed that Cul4A is an important regulator of proliferation, cell cycle progression and tumour growth in lung cancer in this study." (PMID 26969027, 2016). "In H157, H322 and H460 lung cancer cells, knockdown of Cul4A inhibited proliferation of lung cancer cells." (PMID 26969027, 2016). "We first examined CUL4A expression in a panel of 7 human lung cancer cell lines and 2 normal human lung epithelial cell lines." (PMID 25413624, 2014). "Overexpression of CUL4A in human lung cancer cell lines increased cell proliferation, inhibited apoptosis, and subsequently conferred resistance to chemotherapy." (PMID 25413624, 2014). "As expected, EGFR expression was found to be positively correlated with CUL4A level in lung cancer tissues." (PMID 25413624, 2014).
lung carcinoma (continued). "We found that CUL4A was highly expressed in human lung cancer tissues and lung cancer cell lines, and this elevated expression positively correlated with disease progression and prognosis." (PMID 25413624, 2014). "Taking together, these results suggest that CUL4A is an important regulator of proliferation in lung cancer cells in vivo." (PMID 25413624, 2014). "The knockdown of CUL4A expression was shown to increase the chemosensitivity of lung cancer cells." (PMID 34257560, 2021). "In vivo experiments, Cul4A-RNAi combined with gemcitabine chemotherapy inhibited lung cancer tumor growth, suggesting that this combination may provide a new approach for lung cancer treatment." (PMID 33935743, 2021). "Cul4A degraded TGFβ1, and its overexpression promoted resistance to gemcitabine in lung cancer." (PMID 33935743, 2021). "Based on the close relationship between COPD and lung cancer, we speculate that CUL4A may also plays an important role in the development of COPD." (PMID 31060565, 2019). "This study aimed to elucidate the role of Cul4A in lung cancer invasion and metastasis." (PMID 31052599, 2019). "Since other annexin proteins, including ANXA1, A2, and A7 have been observed to be regulated by ubiquitination, we thus postulated that ANXA10 may also be regulated by Cul4A through ubiquitination in lung cancer cells." (PMID 31052599, 2019). "Cul4A overexpression in the H460 lung cancer cells resulted in lowered protein levels of ANXA10." (PMID 31052599, 2019). "We hypothesized that Cul4A mediated degradation of ANXA10 was one of the key mechanisms in lung cancer invasion and metastasis." (PMID 31052599, 2019). "Study of Cul4A in NSCLS shows that Cul4A overexpression promotes docetaxel and doxorubicin resistance in lung cancer cells, it may attribute to EGFR transcriptional expression and antiapoptosis of NSCLC cells regulated by Cul4A10." (PMID 30718461, 2019). "Notably, knockdown of p21 by siRNA was observed to decrease chemosensitivity in Cul4A knockdown H157, H157 and H460 lung cancer cells." (PMID 26969027, 2016). "In summary, our study showed that targeting Cul4A with RNAi or other techniques may provide a possible insight to the development of lung cancer therapy in the future." (PMID 26969027, 2016). "Increased chemosensitivity to pemetrexed was observed in Cul4A knockdown H460 lung cancer cells." (PMID 26969027, 2016). "In H460 lung cancer cell line, higher expression of TGFBI was noted compared to the expression of TGFBI in H157 and H322 lung cancer cell lines, which may account for increased sensitivity to gemcitabine after knockdown of Cul4A in H460 lung cancer cell line." (PMID 26969027, 2016). "Our results indicate that Cul4A may regulate chemosensitivity through various mechanisms in different lung cancer cells and further studies are warranted." (PMID 26969027, 2016). "In addition, we also observed that increased chemosensitivity to gemcitabine was observed after knockdown of Cul4A in lung cancer cells and vice versa." (PMID 26969027, 2016). "Transient overexpression of Myc‐tagged Cul4A was also performed in H1975 lung cancer cells." (PMID 26969027, 2016). "We first investigated the expression of Cul4A in lung cancer cell lines and found that overexpression of Cul4A was noted in six lung cancer cell lines (H322, H460, A549, H838, H157 and H1703) out of eight cell lines compared to the expression of Cul4A in a normal lung cell line (WI‐38)." (PMID 26969027, 2016). "Thus, we studied the expression of TIEG1 and TGFBI in Cul4A shRNA transfected stable lung cancer cells." (PMID 26969027, 2016). "Less chemosensitivity to pemetrexed was observed in Cul4A knockdown H157 lung cancer cells." (PMID 26969027, 2016). "As a result, targeting Cul4A with small molecules, RNAi, or other techniques may provide a possible insight to the development of lung cancer therapy as well as other cancers." (PMID 26969027, 2016).
lung carcinoma (continued). "Increased chemosensitivity after Cul4A knockdown may be partially related to the up‐regulation of p21 in lung cancer cells." (PMID 26969027, 2016). "Different expressions of TIEG1 and TGFBI in lung cancer cell lines after Cul4A knockdown or expression may indicate different pathways for gemcitabine chemosensitivity in different lung cancer cells." (PMID 26969027, 2016). "Up‐regulation of p21 was also observed in lung cancer cells after Cul4A knockdown in our study." (PMID 26969027, 2016). "We showed that Cul4A is overexpressed in lung cancer cells and tissues." (PMID 26969027, 2016). "The mechanism of increased sensitivity to gemcitabine after knockdown of Cul4A in lung cancer cell lines remains unknown." (PMID 26969027, 2016). "Our results may provide another evidence that targeting Cul4A may add to increase chemosensitivity in platinum‐based chemotherapy in lung cancer patients." (PMID 26969027, 2016). "Notably, decreased tumour growth and increased chemosensitivity to gemcitabine were also noted after Cul4A knockdown in lung cancer xenograft nude mice models." (PMID 26969027, 2016). "To test whether CUL4A overexpression regulates lung cancer cells transformation, we examined anchorage-independent cell growth by soft agar colony formation assay." (PMID 25413624, 2014). "Our study showed that the overexpression of Cul4A was associated with the downregulation of the tumor suppressor ANXA10 in lung cancer tissues and cells, which may provide another mechanism for the role of Cul4A in lung cancer invasion and metastasis." (PMID 31052599, 2019). "Furthermore, in vitro and in vivo studies showed decreased tumor growth and increased chemo-sensitivity to gemcitabine through G0/G1 cell cycle arrest after Cul4A (cullin 4A) knockdown, which is an important regulator of proliferation and cell cycle progression in lung cancer." (PMID 29799499, 2018). "Additionally, knockdown of Cul4A increased expression levels of TGFBI in H460 lung cancer cells." (PMID 26969027, 2016). "Our previous study consistently showed an inverse correlation between CUL4A and XPC or P21 in lung carcinoma patients." (PMID 32587774, 2020). "A significant reduction in lung metastasis was observed in the Cul4A knockdown groups of H460 using FMT imaging and A549 lung cancer cells." (PMID 31052599, 2019). "Further experimentation revealed that Cul4A regulates ANXA10 through ubiquitination and protein degradation in lung cancer cells." (PMID 31052599, 2019). "We found that knockdown of Cul4A also resulted in increased expression levels of TIEG1 in H157 and H322 lung cancer cells." (PMID 26969027, 2016). "Lower expression of Cul4A was observed in PC9 and HCC827 lung cancer cell lines compared to normal lung cell line (WI‐38)." (PMID 26969027, 2016). "Moreover, increased expression of p21, transforming growth factor (TGF)‐β inducible early gene‐1 (TIEG1) and TGF beta‐induced (TGFBI) was observed in lung cancer cells after Cul4A knockdown, which may be partially related to increased chemosensitivity to gemcitabine." (PMID 26969027, 2016). "Collectively, our data showed that CUL4A promotes NSCLC cell proliferation through EGFR-AKT pathway and high level of CUL4A expression sensitizes lung cancer cells to erlotinib." (PMID 25413624, 2014). "Notably, Cul4A regulated the degradation of ANXA10 through its interaction with ANXA10 and ubiquitination in lung cancer cells." (PMID 31052599, 2019). "IC50 values in Cul4A knockdown H157 lung cancer cells were not determined, but significantly growth inhibition to pemetrexed was observed." (PMID 26969027, 2016). "On the contrary, lower expression of TGFBI was noted in H157 and H322 lung cancer cell lines, and up‐regulation of TIEG1 may account for increased sensitivity to gemcitabine after knockdown of Cul4A in these two cancer cell lines." (PMID 26969027, 2016).
lung carcinoma (continued). "In our study, different lung cancer cells showed different expressions of TIEG1 and TGFBI after Cul4A knockdown or expression, which may indicate different pathways for gemcitabine chemosensitivity in different lung cancer cells." (PMID 26969027, 2016). "Poorly expressed CDT1 has been reported to be evident following Cul4A overexpression‐induced transgenic mouse model of lung tumorigenesis, and Cul4A depletion contributed to increased sensitivity to chemotherapy drug cisplatin by elevating CDT1 expression in lung cancer cells." (PMID 33655712, 2021). "Furthermore, we identified the specific roles of CUL4A and CUL4B in lung cancer." (PMID 32587774, 2020).
colorectal cancer (13 papers, 2015 to 2025). A primary or metastatic malignant neoplasm that affects the colon or rectum. "A very recent study has shown that loss of Cul4A expression underlies cisplatin hypersensitivity in colorectal carcinoma cells with acquired trabectedin resistance." (PMID 30718461, 2019). "The transcription factor c-Myc and two cullin family members CUL4A/4B function as oncogenes in colorectal cancer." (PMID 32140074, 2020). "In colorectal cancers, overexpression of Cul4A induces the epithelial–mesenchymal transition through the regulation of H3K4 trimethylation at the E-cadherin, N-cadherin, and vimentin gene promoters." (PMID 31052599, 2019). "A recent study showed that trabectedin-resistant colorectal carcinoma cells were hypersensitive to cisplatin after losing Cul4A expression." (PMID 30718461, 2019). "This complex binds to the promoter of CUL4A/4B and induces its expression, activating the CUL4A/4B‐associated E3 ligase‐CRL4, which leads to the ubiquitination and degradation of ST7 by the CRL4 E3 ligase, promoting the occurrence of colorectal cancer." (PMID 39964832, 2025). "Cullin 4A and 4B (CUL4A and 4B) function as oncogenes in colorectal cancer (CRC) cells." (PMID 32140073, 2020). "One exception is our recent finding in which CUL4A/4B are both overexpressed in colorectal cancer." (PMID 32140074, 2020). "In colorectal cancer, PHGDH undergoes monoubiquitylation by cullin 4A, which enhances its activity and promotes tumor cell migration and colorectal cancer metastasis through SAM-mediated histone methylation." (PMID 39207107, 2024).
prostate carcinoma (12 papers, 2012 to 2025). A carcinoma that arises from epithelial cells of the prostate gland. "The positive correlation between the high expression of CUL4A and thalidomide sensitivity was also demonstrated in prostate cancer cell lines." (PMID 34207079, 2021). "A recent study has shown that CUL4A activates ERK pathway, and that U0126 inhibits CUL4A-induced invasion in prostate cancer cells." (PMID 23272222, 2012). "In addition, prostatic cancers harboring highly expressed CUL4A were found to have poorer overall survival, while knockdown of CUL4A inhibits cancer cell growth in vitro and in vivo." (PMID 28576144, 2017). "In addition, prostate cancer cells with high expression of CUL4A are sensitive to thalidomide, and apoptosis to thalidomide also depends on high level of CUL4A." (PMID 26460955, 2015). "Screening of CUL4A level in prostate cancer patients benefits to determine whether some patients should accept therapy of thalidomide." (PMID 26460955, 2015). "In the PPI network (up regulated), genes such as CUL4A and GLRX3 were responsible for the invasion of many cancer types such as prostate cancer and oral squamous cell carcinoma, but these genes may be identified with the invasion of GBM." (PMID 31137733, 2019).
gastric cancer (8 papers, 2016 to 2025). A primary or metastatic malignant neoplasm involving the stomach. "CUL4A can induce increased expression of NF-kB, and neddylated CUL4A preferentially binds to DNA methyltransferase (DNMT3b), thus inhibiting the formation of chromatin and gastric cancer development." (PMID 37777749, 2023). "In gastric cancers, overexpression of Cul4A promoted gastric cancer cell proliferation and epithelial–mesenchymal transition by downregulating LATS1-Hippo-YAP signaling." (PMID 31052599, 2019). "Although Cullin 4A (CUL4A) is mutated or amplified in several human cancer types, its role in gastric cancer (GC) and the mechanisms underlying its regulation remain largely uncharacterized." (PMID 26840256, 2016). "Therefore, it can be speculated that CUL4A promotes the encroachment and spread of malignant cells through this pathway in gastric cancer." (PMID 38313020, 2024).
non-small cell lung carcinoma (7 papers, 2014 to 2022). A group of at least three distinct histological types of lung cancer, including non-small cell squamous cell carcinoma, adenocarcinoma, and large cell carcinoma. "Previously, FBXW5 was proposed to form a complex with CUL4A in non-small cell lung cancer, which led to the degradation of the tumor suppressor protein, DLC1, a Rho GTPase-activating protein, ultimately promoting cell proliferation." (PMID 35210431, 2022). "Decreased miR-363-3p expression contributes to the drug resistance of non-small cell lung cancer cells by regulating CUL4A expression." (PMID 35166647, 2022). "CUL4A has highly expressed in non-small cell lung cancer (NSCLC) tissues and can promote lung cancer progression by inducing EMT." (PMID 36045410, 2022). "CUL4A has been proposed as oncogene in several types of human cancer, but its clinical significance and functional role in human non-small cell lung cancer (NSCLC) remain unclear." (PMID 25413624, 2014).
liver cancer (6 papers, 2011 to 2024). An epithelial or non-epithelial malignant neoplasm that arises from the liver. "Cul4A has been implicated in multiple cancers, namely breast, mesothelioma, lung, and liver cancers." (PMID 31052599, 2019). "The Cul4A gene is amplified in human breast and liver cancers, and loss-of-function of Cul4 results in the accumulation of the replication licensing factor CDT1 in Caenorhabditis elegans embryos and ultraviolet (UV)-irradiated human cells." (PMID 21989042, 2011). "Also, PHF8 functions as an oncogene during liver cancer pathogenesis through increasing the expression of Cullin 4A (CUL4A), a regulator of EMT." (PMID 39311138, 2024). "For example, by inhibiting CUL4A-mediated LATS1 ubiquitination and increasing YAPS127 phosphorylation, lncRNA uc.134 can inhibit the progression of liver cancer." (PMID 34925511, 2021).
malignant pleural mesothelioma (6 papers, 2014 to 2025). A malignant neoplasm that arises from mesothelial cells in the pleura and shows a diffuse growth pattern. "Recently, it has benn shown that CUL4A is overexpressed and amplified in 64% primary malignant pleural mesothelioma, and downregulation of CUL4A with shRNA causes cell cycle arrest and growth inhibition through upregulation of p21 and p27 proteins." (PMID 25413624, 2014).